LAG3 (lymphocyte activating 3)
Diseases named in the same sentence as LAG3 in open-access papers (continued):
Sharing a sentence is not in itself a finding about the gene and the disease.
autoimmune hepatitis (2 papers, 2023 to 2025). Hepatitis caused by autoantibodies. "Another study focusing on autoimmune hepatitis (AIH)/PBC variants found that the levels of expression of soluble LAG3, TIM3, CD86, and CD25 in AIH were higher and could be differentiated from PBC." (PMID 39859319, 2025).
basal cell carcinoma (2 papers, 2022). A carcinoma involving the basal cells. "High levels of soluble PD1/PDL1 and lymphocyte-activation gene 3 (LAG-3) were detected in basal cell carcinoma patients, which may serve as prognostic/predictive biomarkers." (PMID 36479137, 2022).
cervical disease (2 papers, 2021 to 2026). "What stood out in the tables was the patients afflicted with the cervical disease showed positive correlation significantly, such as famous immune checkpoint genes (CTLA4, TIGIT, HAVCR2, LAG3, etc.)and costimulatory genes like ICOS, CD80, CD40, and so forth." (PMID 33694292, 2021).
chordoma (2 papers, 2021 to 2022). Chordomas are rare malignant tumors arising from embryonic remnants of the notochord in axial skeleton. "The effects of many immune checkpoints, including LAG3, TIM3, SIRPα, HHLA2, MAGEA4, VISTA and TIGIT, have been validated in chordoma, and five of them (TIM3, SIRPα, HHLA2, MAGEA4 and VISTA) were only evaluated in preclinical study." (PMID 36612259, 2022).
chronic hepatitis (2 papers, 2017 to 2020). An active inflammatory process affecting the liver for more than six months. "Among them programmed death-1 (PD-1), cytotoxic T-lymphocyte antigen 4 (CTLA-4), T-cell immunoglobulin and mucin domain-containing protein 3 (TIM-3) and Lymphocyte-activation gene 3 (LAG-3) have been studied in chronic hepatitis and HCC." (PMID 32878115, 2020). "Other negative T cell inhibitory molecules, including natural killer cell receptor CD244, lymphocyte-activation gene 3 (LAG-3), T cell immunoglobulin domain and mucin domain-3 (Tim-3), CD160, and adenosine A3 receptor (A3AR) are related to T cell dysfunction in chronic hepatitis and HCC." (PMID 28703774, 2017).
clear cell ovarian cancer (2 papers, 2023 to 2025). "In clear cell ovarian cancer, increased LAG-3 expression in tumor-infiltrating lymphocytes was associated with FIGO stages III and IV and in cases of cancer recurrence." (PMID 40649775, 2025). "LAG-3 has been studied in various gynecological cancers: endometrioid endometrial cancer, high-grade serous ovarian cancer (HGSOC), and clear cell ovarian cancer." (PMID 40649775, 2025).
cutaneous T cell Lymphoma (2 papers, 2021 to 2023). "The TNBC cell lines express high levels of PD-L1 and CTLA-4, but low levels of LAG-3, whereas the HuT-78 cells, derived from cutaneous T cell Lymphoma, express high levels of LAG-3." (PMID 35008285, 2021).
differentiated thyroid carcinoma (2 papers, 2023 to 2024). Differentiated thyroid carcinoma (DTC), also known as papillary or follicular thyroid carcinoma, is a slow-growing malignancy usually presenting in adults as an asymptomatic thyroid mass. "In papillary thyroid carcinoma (PTC), which is the most common form of well-differentiated thyroid cancer, most checkpoint molecules, including LAG-3, PD-1, ICOS, and IDO1, are significantly reduced compared to TIM-3, whose expression is significantly enriched." (PMID 37567938, 2023).
dysplasia (2 papers, 2019 to 2022). A usually neoplastic transformation of the cell, associated with altered architectural tissue patterns. "We found that the expression of inhibitory receptors such as PD‐1, TIM‐3, and LAG‐3 increased successively from normal, dysplasia to carcinoma tissues." (PMID 35179267, 2022).
Erythema (2 papers, 2021 to 2023). Redness of the skin, caused by hyperemia of the capillaries in the lower layers of the skin. "Three studies were identified that demonstrated that the use of LAG‐3 inhibitors, whether as a single agent or in combination with other immune checkpoint inhibitors, resulted in stomatitis, pruritus, rash, dry skin, erythema and vitiligo." (PMID 38047262, 2023).
esophageal tumor (2 papers, 2020 to 2022). "LAG3 shows a fourfold higher expression in primary untreated esophageal tumor in comparison to healthy normal tissue." (PMID 31960110, 2020).
Ewing sarcoma (2 papers, 2021 to 2023). A small round cell tumor that lacks morphologic, immunohistochemical, and electron microscopic evidence of neuroectodermal differentiation. "A subpopulation of Ewing sarcoma–associated CD8+ T cells shows elevated levels of dysfunction as indicated by high levels of LAG-3 expression." (PMID 37823774, 2023). "We examined the immunohistochemical expression of checkpoint receptors PD-1, TIM-3, LAG-3 and their respective ligands in various pediatric cancers at diagnosis and found high expression of TIM-3/Galectin-9 in the infiltrating cells of Ewing sarcoma." (PMID 35938052, 2021). "In Ewing sarcoma samples, only PD-L1, LAG-3, and MHC class II were negative on tumor cells, and LAG-3 was also negative on non-tumor cells." (PMID 35938052, 2021).
immune deficiency (2 papers, 2017 to 2022). "The study on Anaplasma marginale infection in cattle indicated that the percentages of CD4+ and CD8+ T cells expressing both of PD-1 and LAG-3 were increased during acute phase, suggesting that the PD-1+ LAG-3+ T cells contributes to the immune deficiency observed in this infection." (PMID 28445479, 2017). "Increased expression of IC proteins, such as PD-1, Tim-3, Lymphocyte activation gene 3 (LAG-3), and CTLA-4, resulting in T cell exhaustion is the major reason for T cell immunodeficiency in MM." (PMID 36439426, 2022).
liver cirrhosis (2 papers, 2020 to 2023). "We found significantly higher expression of markers of T-cell senescence (e.g., PTPRC, TIGIT, and TNF) and exhaustion (e.g., PDCD1, CTLA4, LAG3, and TNFRSF9) in hepatic CD4+ and CD8 + T cells in participants with NASH or liver cirrhosis than in controls." (PMID 37735474, 2023). "Genes related to senescence (e.g., PTPRC, TIGIT, and TNF) and exhaustion (e.g., PDCD1, CTLA4, LAG3, and TNFRSF9) were highly enriched in CD4+ and CD8 + T cells from the participants with liver cirrhosis." (PMID 37735474, 2023).
malignant mesothelioma (2 papers, 2022 to 2024). A malignant neoplasm of the pleura or peritoneum, arising from mesothelial cells. "The primary objective of this study was to advance our understanding of the malignant mesothelioma TIME while examining the protein expression levels for LAG3, BAP1, NF2, and methylthioadenosine phosphorylase (MTAP)." (PMID 38994676, 2024). "We next investigated the influence of the protein expression of BAP1, NF2, CDKN2A, and LAG3 on the malignant mesothelioma TIME." (PMID 38994676, 2024). "In addition to the immune checkpoint LAG3, BAP1, NF2, and MTAP were chosen as proxies to represent commonly altered TSG products in malignant mesothelioma." (PMID 38994676, 2024).
memory impairment (2 papers, 2023 to 2025). "Interestingly, LAG-3 is potentially expressed in the central nervous system including microglia cells, which potentially could be of relevance in relation to the association of sLAG-3 with memory impairment." (PMID 40519925, 2025).
Miscarriage (2 papers, 2024 to 2025). A pregnancy that ends at a stage in which the fetus is incapable of surviving on its own, defined as the spontaneous loss of a fetus before the 22th week of pregnancy. "Women with certain ICP profiles (e.g., low PD-1 or LAG-3 expression on T-cells) may be at higher risk for miscarriage." (PMID 39273326, 2024). "A decrease in the number of LAG-3+dCD4+T cells was correlated with miscarriage." (PMID 41023624, 2025). "In conclusion, our study concluded the higher LAG-3 expression on dCD4+T cells during normal pregnancy is beneficial, and decreased LAG-3 on dCD4+T cells might be associated with miscarriage." (PMID 41023624, 2025). "However, our study showed that pregnant CBA/J females treated with LAG-3 blocking antibodies became more susceptible to fetal loss, indicating that the reduction proportions and the functional abnormity of LAG-3 might be one of the contributing factors to miscarriage." (PMID 41023624, 2025).
neuroblastoma (2 papers, 2020 to 2023). Neuroblastoma (NB) is the most common solid, extracranial childhood tumor. "In contrast, co-incubation with different neuroblastoma cells yielded mixed results on the expression of PD-1, TIM3 and LAG3 inhibitory receptors on CAR T cells." (PMID 32296437, 2020).
osteoarthritis (2 papers, 2020 to 2023). A noninflammatory degenerative joint disease occurring chiefly in older persons, characterized by degeneration of the articular cartilage, hypertrophy of bone at the margins and changes in the synovial membrane. "Peripheral blood mononuclear cells (PBMCs) from RA, osteoarthritis (OA) patients and healthy volunteers were collected for flow cytometry staining of LAG3+ B cells." (PMID 37143367, 2023). "Lymphocyte activation gene-3 (LAG-3+) regulatory T cells (Treg cells) have also been shown to increase in osteoarthritis." (PMID 32189997, 2020). "Evidence showed that the response of Treg cells decreased in osteoarthritis in concurrent with an increase of LAG-3 expression in osteoarthritis." (PMID 32189997, 2020).
papillary thyroid cancer (2 papers, 2022 to 2023). "Another study showed the opposite, where both anaplastic and papillary thyroid cancer showed increased LAG-3 expression, among other immune checkpoint mediators such as PD-L1, PD-L2, PD-1, and TIM-3." (PMID 37509517, 2023). "One study showed that patients with papillary thyroid cancer have relatively lower expression of LAG-3 compared to normal healthy thyroid tissue." (PMID 37509517, 2023). "Conversely, in papillary thyroid cancer most checkpoint molecules, including LAG-3, PD-1, inducible T cell COStimulator (ICOS), and indoleamine 2,3-Dioxygenase 1 (IDO1), were significantly decreased compared with healthy thyroid tissues." (PMID 36077354, 2022). "However, data on the significance of LAG-3 expression in papillary thyroid carcinomas are more discordant." (PMID 37509517, 2023).
prion disease (2 papers, 2018 to 2020). A transmissible disease that is caused by a protein that is able to induce abnormal folding of normal cellular proteins, leading to characteristic spongiform brain changes, which are associated with neuronal loss without an inflammatory response. "Even then, however, the increase of Lag3 expression seemingly contributed nothing to the pathogenesis of prion diseases." (PMID 30279468, 2018). "Here we examined the expression levels of Lag3 in the mouse brain after prion infection and investigated its possible role in the progression of prion diseases by using Lag3 knockout (Lag3 KO) mice." (PMID 30279468, 2018). "We failed finding any significant difference between the Lag3 WT and KO mice regarding the PrPSc load, prion-induced neurotoxicity, astrocyte and microglia reactions and inflammatory gene expression in the brain at the terminal stage of prion diseases." (PMID 30279468, 2018). "Here we examined the possible role of Lag3 in the pathogenesis of prion diseases." (PMID 30279468, 2018). "To investigate the possible involvement of Lag3 in the pathogenesis of prion diseases, we firstly examined its expression levels in the mouse brains inoculated with scrapie prions (Rocky Mountain Laboratory, Passage 6; RML6) or with non-infectious brain homogenate (NBH)." (PMID 30279468, 2018). "Whether and how Lag3 may contribute to the pathogenesis of other similar neurodegenerative conditions, such as prion diseases, is unclear." (PMID 30279468, 2018). "We conclude that loss of Lag3 has no significant influence on prion disease pathogenesis." (PMID 30279468, 2018). "Loss of Lag3 had no significant influence on prion disease pathogenesis." (PMID 30279468, 2018). "Through western blot combining with proteinase K (PK) digestion, we found that there were similar levels of PK-resistant PrPSc in the brains of Lag3 WT and KO mice, which indicates that loss of Lag3 does not affect the generation of pathologic PrP aggregates in prion diseases." (PMID 30279468, 2018). "The lack of LAG3 involvement in the pathogenesis of prion disease may further support the fact that it is specific for PD, and potentially able to differentiate from “pure” prionopathies, such as CJD." (PMID 32340360, 2020). "However, Lag3 seemed to play no role in regulating microglial activation and inflammatory gene expression in prion diseases." (PMID 30279468, 2018). "Considering that Lag3 is an immune checkpoint receptor, our results suggest that immune checkpoint inhibition (an increasingly prevalent therapeutic modality against many types of cancer) might not exert positive or negative effects on the progression of prion diseases." (PMID 30279468, 2018).
recurrent disease (2 papers, 2018 to 2021). "As the two morphological parameters refer to cellular size and complexity, these findings suggest that in relapsing tumors a higher expression of LAG-3 is characteristic of small (FSC-Alow) resting (SSC-Alow) T cells." (PMID 34944798, 2021).
retinoblastoma (2 papers, 2019 to 2023). A malignant tumor that originates in the nuclear layer of the retina. "In retinoblastoma (RB), the expression of LAG3 exhibited a positive correlation with angiogenesis and inflammation, suggesting its regulatory roles in shaping of tumor microenvironment." (PMID 38115039, 2023). "Induction of LAG3 expression was moderate and varied with retinoblastoma cell type." (PMID 31500597, 2019). "Expression of the LAG3, TIM3 and PD1 inhibitory receptors were also assessed after retinoblastoma encounter by flow cytometry analysis." (PMID 31500597, 2019).
Thrombocytopenia (2 papers, 2024 to 2026). A reduction in the number of circulating thrombocytes. "Furthermore, we found interesting associations between LAG-3 and platelet count, suggesting its role in thrombocytopenia, a hallmark of HFRS severity." (PMID 38792573, 2024).
uterine cancer (2 papers, 2023 to 2025). Primary or metastatic malignant neoplasm involving the uterine corpus and/or the cervix. "One study found that uterine cancer patients with high levels of the immune checkpoint protein LAG-3 had a poorer response to pembrolizumab." (PMID 37511876, 2023). "The ‘Genotype’ hypothesis findings for uterine cancer showed that the expression of the genes CMC2, CXCL13, CXCL19, LAG3, SRD5A2, and others had changed." (PMID 40847033, 2025).
vitiligo (2 papers, 2023 to 2024). Generalized well circumscribed patches of leukoderma that are generally distributed over symmetric body locations and is due to autoimmune destruction of melanocytes. "Thus, the effect of rs781745126-T is akin to drugs that inhibit LAG-3, which unleash immune responses and can have thyroid dysfunction and vitiligo as adverse events." (PMID 38982041, 2024).
abortion (1 paper, 2025). the ending of pregnancy by removing a fetus or embryo before it can survive outside the uterus. "To further clarify whether functional regulation of LAG-3 on CD4+T cells is involved in pregnancy maintenance, we first compared LAG-3 expression on dCD4+T cells from mouse model representing normal pregnancy and those prone to abortion." (PMID 41023624, 2025).
Achalasia (1 paper, 2023). A disorder of esophageal motility characterized by the inability of the lower esophageal sphincter to relax during swallowing and by inadequate or lacking peristalsis in the lower half of the body of the esophagus. "Besides, many co-inhibitory molecules, including PDCD1, HAVCR2, LAG3, ICOS, PRDM1, and MAF, were markedly downregulated in TRM, supporting an activated cell state in achalasia." (PMID 37542039, 2023).
acinic cell carcinomas (1 paper, 2020). "While 50% of the acinic cell carcinomas and SDC were LAG3 positive, AdCy and ANOS showed no LAG3 staining." (PMID 32232506, 2020).
acute leukemia (1 paper, 2016). A clonal (malignant) hematopoietic disorder with an acute onset, affecting the bone marrow and the peripheral blood. "Several other checkpoint molecules are known and are under investigation in acute leukemia, including CTLA-4, TIM-3, lymphocyte activation gene-3 (LAG-3), and B and T cell lymphocyte attenuator (BTLA)." (PMID 28018601, 2016).
adenoid cystic carcinoma (1 paper, 2020). A malignant tumor arising from the epithelial cells. "In the group of adenoid cystic carcinomas, LAG3 expression was also associated with a shorter event-free survival (EFS)." (PMID 32232506, 2020).
Adrenal insufficiency (1 paper, 2025). Insufficient production of steroid hormones (primarily cortisol) by the adrenal glands. "A comparative analysis of endocrine toxicities associated with PD-1, PD-L1, and LAG-3 inhibitors indicates that the risk of adrenal insufficiency is markedly higher with combination regimens, particularly those incorporating LAG-3 blockade." (PMID 40895685, 2025).
anal carcinoma (1 paper, 2023). "Uniquely for the tumor microenvironment, the higher expression of immune checkpoint biomarkers such as PD-1, PD-L2, LAG-3 and OX40L was observed in the clinically unfavorable cohort of recurrent anal cancer patients." (PMID 36980587, 2023).
anaplasmosis (1 paper, 2018). "In addition, a previous study demonstrated increase of LAG-3+ γδ T cells in peripheral blood of cattle during acute anaplasmosis." (PMID 29914540, 2018).
aneuploidy (1 paper, 2025). Chromosomal disorder consisting of the presence a chromosomal abnormality in which there is an addition or loss of chromosomes within a set. "In addition, it was also found that some immune checkpoint genes (PDCD1, HAVCR2, TIGIT, LAG3) had high expression in high-risk group, which was related to a higher TIDE and aneuploidy scores than in the low-risk group." (PMID 39950044, 2025).
autoimmune thyroid disease (1 paper, 2024). Inflammatory disease of the thyroid gland due to autoimmune responses leading to lymphocytic infiltration of the gland. "Here, the authors conduct a GWAS for autoimmune thyroid disease, finding 225 loci including a start codon variant in LAG3 that confers a 3.4-fold risk of autoimmune thyroid disease and reduces expression and plasma levels of LAG−3." (PMID 38982041, 2024).
bladder tumors (1 paper, 2019). "Findings from our study provide compelling evidence for co-expression of multiple immune checkpoint genes including, PD-1, PD-L1, IDO1, TIGIT, TIM-3, TGFB1, LAG3, and others, that potentially contribute to compensatory immune evasion in bladder tumors." (PMID 31174611, 2019).
bone marrow failure (1 paper, 2022). "In this study, we investigated the mutations in patients with bone marrow failure diseases using Sanger sequencing to identify association of genetic variations in LAG3 with these diseases." (PMID 35265454, 2022).
bone marrow failure syndrome (1 paper, 2025). "Donor LAG3 rs870849 genotypes have been linked to adverse outcomes following allogeneic stem cell transplantation, while other LAG3 polymorphisms have been associated with altered immune recovery in bone marrow failure syndromes." (PMID 41614836, 2025).
brain glioma (1 paper, 2024). A malignant glioma that involves the brain. "However, we cannot deny that α-synuclein/LAG-3 interacts under pathological conditions, for example, LAG-3 can be significantly expressed in brain gliomas." (PMID 39252941, 2024).
brucellosis (1 paper, 2024). Brucellosis is a bacterial infection that spreads from animals to people via unpasteurized dairy products or by exposure to contaminated animal products or infected animals. "Further analysis found that Th1 cells had the highest exhaustion scores in brucellosis patients, and highly expressed multiple inhibitory receptors (e.g., LAG3, CD160, CTLA4)." (PMID 39135683, 2024). "The exhausted NK cells (NK_CD56(dim)) highly expressed multiple inhibitory molecules (e.g., LAG3, CD244, CTLA4) in brucellosis patients compared to healthy donors." (PMID 39135683, 2024).